CRP (C-reactive protein)
Diseases named in the same sentence as CRP in open-access papers (continued):
Sharing a sentence is not in itself a finding about the gene and the disease.
infection (continued). "One patient who underwent TTIDF had recurrent infection with elevated CRP during follow-up and complained of back soreness." (PMID 29049254, 2017). "As expected, patients with infection had higher levels of blood leukocytes, CRP and plasma IL-6 levels." (PMID 28500294, 2017). "The concentration of CRP, a plasma protein, rises dramatically as a result of cytokine-mediated responses to most forms of infection, inflammation, and tissue injury." (PMID 29091955, 2017). "Most inflammatory markers, such as interleukin-6 (IL-6), tumor necrosis factor-α (TNF-α), CRP, and fibrinogen, increased significantly in response to infection and in active diseases states." (PMID 28539965, 2017). "CRP is generally thought of as being an inflammatory mediator, due to its upregulation during infection and the correlation of high CRP levels with poor prognosis in persistent inflammatory conditions such as cardiovascular disease." (PMID 28619036, 2017). "In contrast to these findings for pro-inflammatory cytokines, serum CRP concentration raised eight hours after infection." (PMID 28245826, 2017). "The plasma concentration of CRP solely depends on rate of its synthesis, which in turn increases many folds within 48 hours of injury, infection or tissue damage." (PMID 28401944, 2017). "We have observed that burn injury with simultaneous infection of P. aeruginosa resulted log- fold increase from the normal level of serum CRP (normal level = ̃0.6 mg/ml) on day 2 after burn injury in both treated and untreated animals." (PMID 28401944, 2017). "The cut-off levels for CRP were determined from studies conducted in high-income countries that tend to have different ethnicity and pattern of infections." (PMID 28451028, 2017). "ESR, CRP, and PCT proved to have a greater diagnostic accuracy than X-rays in predicting late chronic and early postoperative infections." (PMID 29138696, 2017). "The aim of this study was to differentiate unspecific and self-limiting fever after bronchoscopy from fever due to infection by using serum procalcitonin, C-reactive protein and neutrophil count." (PMID 29179755, 2017). "In all patients serological infection parameters were elevated, mean leucocytes counts were 8.7 ± 2.2 billion/l (range 4.8–16.2) and mean CRP values were 66 ± 61 mg/dl (range 5–343)." (PMID 29178898, 2017). "All pigs had plasma CRP levels <10 mg/L (levels for suspected infection in preterm infants), except 2 pigs during week 2 and 1 pig during weeks 3–4." (PMID 27830761, 2016). "Standard systemic markers of an infection, such as elevated C-reactive protein concentration and/or white blood cell count, are known to be frequently unreliable in the case of implant-infections." (PMID 28773509, 2016). "CRP levels greater than 44 mg/L at one week and 22 mg/L at two weeks were also significant prognostic markers for a deep infection focus with a somewhat higher specificity compared to the CRP level on the day of the positive blood culture." (PMID 27182730, 2016). "It indicates a risk of infection when the CRP concentration is higher than 15 μg/mL and severe infection when CRP concentration reaches 200 μg/mL." (PMID 27013227, 2016). "The AUROC for the prediction of infection (groups 2 + 3 vs group 1) on day 0 was similar for CRP, PCT and ICIS." (PMID 27384242, 2016). "We found that a quarter of our participants had an elevated CRP level confirming the high infection rate observed in many Canadian Inuit children." (PMID 27382488, 2016). "A recent meta-analysis showed only a low sensitivity and specificity for CRP (0.75 and 0.67) to indicate an infection." (PMID 26761003, 2016). "Apart from pro-inflammatory cytokines such as IL-2 and IL-6, C-reactive protein (CRP) is an acute phase protein that is produced in response to infection and inflammation." (PMID 27430576, 2016).
infection (continued). "On the 4th day after infection, CRP levels diminished sharply and damaged hepatocytes began their recovery, similar to the CRP pattern reported in a clinical study." (PMID 27556404, 2016). "We applied a lower threshold in a primary care setting because children are presenting at an earlier stage of their illness (i.e. CRP levels in children with evolving serious infection are likely to be lower than when they arrive in hospital)." (PMID 27716201, 2016). "CRP is a plasma protein and its concentration increases dramatically as a result of cytokine-mediated responses to most forms of tissue injury, infection, and inflammation." (PMID 26859663, 2016). "CRP has been recognized as a good marker of systemic inflammation and a valuable clinical tool in severe infections, but clear cut-off levels to guide clinical decisions in SAB have not been demonstrated." (PMID 27182730, 2016). "In this retrospective study, we evaluated the utility of pleural CRP as a novel biomarker of infection in the pleural space." (PMID 27194820, 2016). "The assay was more sensitive for infections occurring >3 months after arthroplasty and for patients with an elevated C-reactive protein (CRP) or erythrocyte sedimentation rate (ESR)." (PMID 26865683, 2016). "If all children were tested and those with a CRP level ≥ 5 mg/L referred, then the positive predictive value would be even lower (0.8 %) and only 1 in 130 children referred would have a serious infection." (PMID 27716201, 2016). "Infection status can be assessed using biomarkers such as C-reactive protein (CRP), an acute phase protein that becomes elevated in response to the early phase of the inflammatory response (approximately 24–48 h)." (PMID 27391972, 2016). "When the initial infection with Salmonella was 200 counts, the number of Hepatocyte Debris and CRP increased for the first 18 hrs of simulation but then progressively decreased to 0, demonstrating no additional pathology at later stages of the simulation." (PMID 27556404, 2016). "CRP is also used to monitor the postoperative course of surgical trauma following orthopedic implants and to detect prosthetic infection." (PMID 27038614, 2016). "Detection of high concentration of CRP is of comprehensive clinical significance in the diagnoses of severity, progress, prognosis, and therapeutic effect of infection and cancers." (PMID 27013227, 2016). "Our simulated results showed that CRP rose initially after infection, but CRP concentration fell sharply after the infection was cured as part of the “Healing Response”." (PMID 27556404, 2016). "Anti-infection treatment was ineffective, with increased cytokine levels, CRP (107.5 mg/L), and ferritin (15,570.1 ng/mL), indicating grade 4 CRS." (PMID 28002337, 2016). "The patients with R017 infections had a higher mean Charlson’s comorbidity index (OR 1.1, 1–1.21, p = 0.05), lower serum albumin (OR 0.47, 0.31–0.73, p = 0.001) and lower CRP levels (OR 0.96, 0.92–0.99, p = 0.022) than those with other ribotypes." (PMID 28002482, 2016). "Although the median PF values were not different between groups, the other indicators of short- (AGP> 1g/L) and long-term (CRP > 5mg/L) infection status were statistically different, with values 27% and 49% lower, respectively, in the IG." (PMID 26974146, 2016). "In present study, the CRP levels increased significantly in the PCOS group thus exhibiting severe infection." (PMID 27923406, 2016). "Considering the wide inter-individual variation and the multiple factors influencing CRP production, such a study design intends to reproduce a clinical model to ponder ‘CD effect’, ‘surgery effect’ and ‘infection effect’ upon the perioperative CRP levels." (PMID 27551522, 2016). "They showed no considerable difference between groups with monomicrobial and polymicrobial infection except for body mass index (BMI) and serum CRP levels." (PMID 27387172, 2016).
infection (continued). "The prolonged elevated CRP level in one case, and previous infection of operated joint in the second case were the reasons for failures." (PMID 27015812, 2016). "A recent study in Indonesia investigated possible haematological, vascular and inflammatory effects of asymptomatic infection and found evidence of all three in children, with CRP being elevated in both children and adults." (PMID 27386859, 2016). "This study was undertaken to assess CRP concentrations at various time points during SAB infection that would enable to identify patients with complications." (PMID 27182730, 2016). "We found significant difference between proven infection and probable infection subgroups as regards the CRP levels (20.1 ± 3.9 versus 6.5 ± 2.1 mg/L, resp., with p < 0.001) and PSP levels (34.6 ± 11.6 versus 17.9 ± 2.1 ng/mL, resp., with p = 0.019)." (PMID 27689072, 2016). "Another important intervention was fast re-intervention by a surveillance protocol with an abdominal CT-scan with rectal contrast was performed when infection parameters (CRP) and/or clinical symptoms where suspect of a complication." (PMID 27385205, 2016). "To further confirm the link between decreased TWEAK concentrations and septic disease we performed correlation analysis revealing that TWEAK concentrations closely correlated to markers of infection in these patients (CRP, PCT and IL-6)." (PMID 27124414, 2016). "Suspicion should be raised when an athlete complains of groin pain and has signs of infection (i.e., fever, elevated white blood cell count, and elevated C-reactive protein)." (PMID 27703831, 2016). "The strength of our study lies in the fact that we have determined important nutritional markers and indicators of inflammation (CRP) and infection (ESR)." (PMID 27537051, 2016). "In the subgroups of patients with mono-infections, P. vivax cases were more likely to have plasma CRP concentrations above the threshold of 3 mg/L as compared with the age-sex matched controls (25.2%, with an OR of 2.7 (95% CI 1.3–6.3))." (PMID 27386859, 2016). "Larger studies with repeated CRP measurement before and after infection would be needed to explore this." (PMID 27386859, 2016). "Accordingly, CRP above 10 mg/L in plasma is routinely used as a marker of infection in the clinical ward." (PMID 27701463, 2016). "Evaluation of clinical signs and symptoms of infection, C-reactive protein levels and X-ray analysis was performed 3 months after termination of antimicrobial treatment and at scheduled later follow-ups." (PMID 27017334, 2016). "When markers of inflammation or infection were considered, children in MM group had significantly lower levels of CRP and ESR compared to the Fe30F group." (PMID 27537051, 2016). "Thirteen patients (16%) in the unilaterally affected group received oral antibiotic treatment for a suggested soft tissue infection with signs of elevated blood infection (CRP > 5 mg/l)." (PMID 28031030, 2016). "In fact, CRP functions as an early defense against infection in innate immunity, facilitating complement-binding to foreign and damaged cells and enhancing phagocytosis by macrophages." (PMID 27227957, 2016). "It should be noted that the ROC-AUC for 180-day mortality was low but comparable to a previous study investigating PTX3, PCT and CRP in emergency room patients with suspected infection." (PMID 26880104, 2016). "A CRP test in these children allows a serious infection to be excluded in a further 22, which means fewer would have to be referred or receive additional testing." (PMID 27716201, 2016). "CRP is an inflammatory marker and a typical acute phase reactant that increases with inflammation, infection, and trauma; it is produced in the liver in response to cytokines, such as interleukin-6." (PMID 27660715, 2016). "There are studies showing that procalcitonin (PCT) is a valuable marker compared to CRP as an indicator of infection." (PMID 26863002, 2016).
infection (continued). "Serum concentrations of retinol and the supposed presence of infection were determined by high-performance liquid chromatography and C-reactive protein quantification, respectively." (PMID 27792135, 2016). "In general, clinicians considered plasma viscosity better for ‘screening’ and CRP more useful for diagnosis or monitoring of infections or specific inflammatory conditions." (PMID 26852797, 2016). "Gas6 performed better than PCT and CRP, both broadly used to diagnose infection but, because of their poor accuracy in this specific indication, should not be used to predict disease outcome." (PMID 27788141, 2016). "CRP can be considered a good candidate due to its 1000-fold elevation in response to infection and the positive correlation between the serum and pleural CRP levels." (PMID 27194820, 2016). "According to CRP measures and parasite counts, approximately one-third of all children had an infection at baseline (719/1943, 37.0 %)." (PMID 27391972, 2016). "Briefly, the definition of infection that included both CRP and parasitaemia seemed to be the most sensitive to covariate associations." (PMID 27391972, 2016). "sTREM-1 or CRP cannot be used as a marker for the differential diagnosis between infection and disease flare." (PMID 27096761, 2016). "An enzyme linked immunosorbent assay (ELISA) was performed for evaluation of CRP, B2M and Neopterin levels and correlated with clinical and microbiological parameters including strain of infection." (PMID 26951717, 2016). "Previous studies comparing the diagnostic performance for infection of a single value of CRP and PCT in different clinical scenarios showed that, at the day of diagnosis, the AUC of CRP was always higher than of PCT." (PMID 27076187, 2016). "Not all SF measurements were considered with C-Reactive Protein (CRP) levels; therefore, it was unclear if SF levels were raised in reflection of greater iron stores or in response to infection and inflammation." (PMID 26891320, 2016). "Difference between ECMO and patient temperature, changes in hemodynamics, and purulent secretions in combination with elevated biomarkers of infection like C reactive protein should raise suspicion of new infection." (PMID 27127794, 2016). "Maternal serum CRP has been proposed as a marker of infection and inflammation in several diseases and MIAC and HCA." (PMID 26942752, 2016). "C reactive protein (CRP) is an inflammatory marker that rises in response to infection or inflammation." (PMID 27458336, 2016). "The third step reported as part of this process was the review and planning of further investigations, with C-reactive protein regarded as a key biological indicator of infection during this phase of management." (PMID 27938372, 2016). "It is also the first to look at post-operative CRP trends comparing children who required one versus multiple surgeries for eradication of infection." (PMID 27174186, 2016). "Increases of ASAT and the ASAT/ALAT ratio are related to cardiac muscle damage, while those of ALAT and CRP are intimately related to liver damage and infection, respectively." (PMID 27366752, 2016). "CRP is released by the liver in response to stress, infection, and/or damage, and the debris simulates dead and dying hepatocytes." (PMID 27556404, 2016). "We found that CRP levels were significantly increased in patients with polymicrobial infection reaching a median of 8.8 mg/L." (PMID 27387172, 2016). "This susceptibility was attributed to a reduced binding and clearance of CRP-opsonised bacteria, resulting in overwhelming infection [90•]." (PMID 27909648, 2016). "We also observed that 9.5 % (n = 14) of the women were classified as having systemic inflammation (hs-CRP ≥ 10 mg/L), suggesting a possible acute response to infection." (PMID 26880234, 2016). "Increased levels of CRP are related to infection,age, body volume index, smoking, drug anddietary habits." (PMID 27054123, 2016).
infection (continued). "The acute phase proteins α-1-AGP and CRP are normally elevated in plasma as a result of injury, infection or inflammation." (PMID 27809921, 2016). "Clinical infection related to the mesh defined as fever, redness of the wound and elevated serum C-reactive protein levels was observed in five (15%) children." (PMID 26793594, 2016). "The CRP serum concentration was highest in patients with S. aureus infection or infection with Streptococcus spp., considerably lower in infection with the other bacteria (S. epidermidis, other Staphylococcus spp." (PMID 28773989, 2016). "CRP levels higher than 108 mg/L on the day of the positive blood culture significantly suggested the presence of a deep infection focus with an acceptable sensitivity of 0.77." (PMID 27182730, 2016). "Some laboratory tests should be requested, such as erythrocyte sedimentation rate and the level of C-reactive protein (CRP) when infection is a suspicion." (PMID 28924354, 2016). "IL-6 is a pro-inflammatory cytokine secreted by T cells and macrophages during infection and after tissue damage; CRP is an acute-phase protein that increases after IL-6 section." (PMID 26275545, 2016). "In the 5% of cases with no cultured bacteria our cut off for infection would be an elevated leukocyte count of >25000 /μl in the joint fluid and/or other clinical data suggesting infection like elevated CRP/blood leucocytes or local abnormalities." (PMID 26997914, 2016). "We used CRP levels and Hepatocyte Debris to reflect the level of tissue damage that occurred after infection." (PMID 27556404, 2016). "The area under the receiver operating characteristic curve (AUROC) for the prediction of infection was 0.70 for CRP, 0.71 for PCT and 0.73 for ICIS (P < 0.001)." (PMID 27384242, 2016). "CRP is an acute phase plasma protein synthesized in the liver which rises rapidly in response to infection or tissue injury." (PMID 27352030, 2016). "We found that overweight and obese patients or those with elevated CRP levels had a greater risk of polymicrobial PJI and hence they were predisposed to recurrence of infection." (PMID 27387172, 2016). "The correlation analysis revealed a significant correlation between LBP and CRP at 6 h (P <0.001), 12 h (P = 0.003) and 3 d (P <0.001), IL-10 and IL-6 at 7 d (P <0.001), and IL-6 and CRP at 7 d (P = 0.001) in patients with infection." (PMID 25613713, 2015). "La prévalence des patients présentant une infection est également plus élevée chez les patients ayant un taux de CRP > 10mg/L comparé à ceux ayant un taux de CRP < 10 mg/L (groupe 2 vs groupe 1 et groupe 3 vs groupe 1, p < 0.05)." (PMID 26301005, 2015). "Iron status was assessed using serum ferritin and hemoglobin, zinc status using serum zinc (standardized to 08:00 collection), and presence of infection/inflammation using C-reactive protein (n = 326)." (PMID 25903453, 2015). "In samples from febrile patients with mono-infections from rural settings in Southeast Asia, CRP was a highly sensitive and moderately specific biomarker for discriminating between viral and bacterial infections." (PMID 26558692, 2015). "Other findings classically associated with infection, including fever and elevated white blood count (WBC), sedimentation rate (ESR), and C-reactive protein (CRP), are uncommon." (PMID 26904745, 2015). "CRP synthesis increases rapidly within hours of tissue injury or infection, which reflects the contribution of CRP to host defence and the innate immune response." (PMID 25910083, 2015). "The present study consists that CRP levels increased in patients with infection, SIRS and worse liver function but the most distinguishable increase was shown in patients with infection." (PMID 26498833, 2015). "The three APR scores, CRP, AG, and Hp, were elevated at age 0 days and then gradually decreased in infection (Group I) and fetal inflammatory response syndrome (Group F)." (PMID 25667565, 2015).